PAX6 (paired box 6)
Diseases named in the same sentence as PAX6 in open-access papers (continued):
Sharing a sentence is not in itself a finding about the gene and the disease.
tumor (continued). "In addition, the results of the multivariate analyses revealed that PAX6 expression level independently predicted poor OS (hazard ratio: 2.542; 95% CI: 1.411–4.579, p = 0.002), as well as the clinical stage, invasion depth, tumor differentiation, and metastasis." (PMID 34459131, 2021). "Mechanistically, exosomal circ007293 acted as an miR-653-5p sponge by inhibiting miR-653-5p activity, thereby increasing the expression of PAX6 in PTC cells and promoting tumor cell proliferation, metastasis, and EMT." (PMID 34866540, 2021). "Compared with A375 cells, A375 xenograft tumor displayed an upregulation for glial and neuronal genes (GFAP, BDNF, MAP2, MTURN, ROBO2, SYT1 and TUBB3) and neural stemness genes (ASCL1, MSI1, PAX6, PDGFRA, SOX9, VIM, ZIC1/2)." (PMID 33468253, 2021). "Paired box 6 (PAX6) is a transcription factor that plays a critical role in tumor suppression, implying that the downregulation of PAX6 promotes tumor growth and invasiveness." (PMID 33182335, 2020). "There is a need for further studies, which should provide further mechanistical explanation for the role of PAX6 in NSCLC, in particular regarding target genes of PAX6 in this tumour group." (PMID 29568088, 2018). "The LM-NSC008.eGFP cells (white arrows) were double positive for Pax6 (red)/eGFP (green), indicating multipotent differentiation of LM-NSC008 cells towards the neuronal lineage in non-tumor bearing naïve mouse brain at 9 months post administration." (PMID 30071048, 2018). "This implicates that DNA methylation is the principle regulatory mechanism of PAX6 inactivation in HCC, suggesting the PAX6 would be a candidate tumor suppressor in the pathogenesis of HCC." (PMID 27110298, 2016). "Under the best cutoff value, 3.4 % of 29 normal controls, 15.6 % of 160 non-tumor tissues, and 39.4 % of 160 HCC tissues were reported as positive for PAX6 methylation (p < 0.0001)." (PMID 27110298, 2016). "We utilized a quantitative methylation-specific PCR (Q-MSP) system for the evaluation of PAX6 methylation in 29 normal controls and 160 paired HCC tissues and their adjacent non-tumor tissues." (PMID 27110298, 2016). "The methylation status of the PAX6 gene was analyzed by Q-MSP in 349 liver tissues, including 29 normal controls and 160 pairs of HCC tissues and their adjacent non-tumor tissues." (PMID 27110298, 2016). "Another potential mediator of the tumor-suppressive ability of miR-135b is SMAD5, which has been recently identified as one of the target of miR-135b activated by the transcription factor PAX6." (PMID 26437223, 2015). "CD133-positive cells, isolated from the tumor, expressed stem cell markers including nestin, CD133, Ki67, Sox2, EFNB1, EFNB2, EFNB3, Cav-1, Musashi, Nucleostemin, Notch 2, Notch 4, and Pax6." (PMID 22995409, 2012). "Both also stain positively for the granule cell marker Pax6, confirming a GNP origin of the tumours." (PMID 20950430, 2010). "However, we did not detect any amino acid mutations of PAX6 in the patient's tumor or lymphocytes." (PMID 20500513, 2010). "Within the Pax6+ clusters 0–9, based on marker gene expression and cell cycle phase, clusters 3, 4, 8 were proliferative (Ki67+) and enriched for the GCP markers Gli1, Atoh1 and Barhl1, indicating highly proliferative GCP-like tumor cells." (PMID 40766638, 2025). "Two significant pathways, hsa04080, Neuroactive ligand-receptor interaction, and hsa04950, Maturity onset diabetes of the young (MODoY; with transcription factors FOXA3, NKX6-1, MAFA, PAX6, PDX1), were identified for the genes expressed more highly in the high-CCNE1 tumours." (PMID 38612869, 2024).
tumor (continued). "p300, BMP, PAX6 (anti-GBM override), HOPX (tumor suppressive + differentiation), NRSF/REST (astrcytogenic but capable of playing oncogenic role), LIF, and TGF beta: BMP is also involved in the neuronal development but it primarily has far greater gliogenic role." (PMID 35538578, 2022). "When PAX6 is upregulated in GBM, it acts as a tumor suppressor." (PMID 35538578, 2022). "Interestingly, eight among the overlapped hypermethylated genes (WT1, PAX6, GNAS, EPB41L1, CSMD1, CPEB1, RERG, and SMAD6) were previously reported to exhibit tumor suppressive functions." (PMID 34462486, 2021). "Immunohistological studies using the cell proliferation marker ki67 and stem cell/tumour cell markers, Nestin and Pax6, showed that these were present in the tumour, but not in the accompanying cortical region." (PMID 33215086, 2020). "Restoration of HDAC complexes in the condensates severely dampens the activation of SS18-SSX downstream genes such as PAX6 and NKX3-2 and almost abolishes the tumorigenicity of SS18-SSX tested by EdU cell proliferation assay, colony formation assay and tumor-bearing mouse models." (PMID 38678233, 2024). "In addition to tumor formation, they observed molecular characteristics of the YAP1–MAMLD1-driven tumor such as high expression of the radial glial neural stem cell marker PAX6, suggesting a transforming role of PAX6+ cells in ST-EPN–YAP1." (PMID 38469231, 2024). "Exosomal circ_007293 was reported to promote proliferation/invasion, migration, and EMT of PTC cells through regulation of the “miR-653-5p/paired box 6 (PAX6)” axis, suggesting that tumor-derived exosomal circRNAs may function as potential biomarkers for cancer progression." (PMID 36230649, 2022). "In a follow-up experiment, we found that upregulated PAX6 expression elevated the expression of EMT marker genes (N-cadherin, vimentin, FSP-1), stem cell biomarkers (CD44, CD133, ALCAM), and the proliferation marker Ki67, yet it inhibited E-cadherin in tumor tissues as assessed by IHC." (PMID 31024010, 2019). "In the present study, the hypermethylation of CpG islands (CGI) of PAX6 was quantitatively investigated in HCC by Q-MSP, with particular attention made to the changes in methylation intensities in primary HCC tissues and their corresponding non-tumor liver tissues." (PMID 27110298, 2016). "If our hypothesis of the tumor cell of origin not being present in the Pax6 TKO retinae, this results suggested that upregulation of Uhrf1 and Hells is only tumorigenic in the context of the tumor cell of origin." (PMID 25338120, 2014). "Additionally, the involvement of GLI1 downstream target genes such as PTCH1, Cyclin D2, Plakoglobin, NKX2.2 and PAX6 have not been studied in either tumor." (PMID 21059263, 2010). "Here, our stage-specific analysis of TCGA mutation data for non-ultramutated EECs showed that KLF3 and PAX6 are SMGs in late-stage (III/IV) but not early-stage (I/II) disease, raising the possibility that KLF3 and PAX6 mutations undergo positive selection during tumor progression." (PMID 35081118, 2022). "Therefore, if the two different deletions were located on the same chromosome, we could not amplify any portions of PAX6 transcript from the tumor tissue including the region that corresponds to the 3′‐side de novo deleted genomic interval." (PMID 20500513, 2010). "We conducted a correlation analysis of the expression of PAX6 and HIF-1α in each tumor sample and found that there was a negative correlation between the two." (PMID 41154694, 2025).
tumor (continued). "In accordance with our data, PAX6 methylation was significantly increased in HBV-positive, HCV-positive, and double-negative HCC tissues as compared with their adjacent non-tumor tissues irrespective of the hepatitis virus status." (PMID 27110298, 2016). "These cells expressed high levels of PAX6 but had only low-level expression of SOX1, whereas the neural precursor stage, which did not result in any tumor formation, expressed high levels of both markers." (PMID 23928330, 2013). "Similarly, our findings also showed that 3 of 6 genes had significantly higher methylation level in tumor tissues than nonmalignant lung tissues, including CALCA, CDH1, and PAX6 genes." (PMID 21639921, 2011).
cancer (49 papers, 2009 to 2025). A tumor composed of atypical neoplastic, often pleomorphic cells that invade other tissues. "Through ATAC-seq, we found that a high expression level of PAX6 elicited enhanced chromatin accessibility, mainly through attenuation of H4K20me3, which typically causes chromatin silence in cancer cells." (PMID 38745318, 2024). "Previous studies have mainly focused on the association between PAX6 promoter methylation and cancer prognosis." (PMID 34459131, 2021). "The role of Pax6 genes in cancer development appears to be linked with their function during organ development." (PMID 25695251, 2015). "The involvement of members from subgroup I (PAX1 and PAX9) and IV (PAX4 and PAX6) in cancer processes seem less significant." (PMID 40506992, 2025). "MethSig cancer genes were also enriched in developmental genes (for example, PAX6, PAX8 and TBX4), suggesting a potential role for DNA methylation in cell plasticity." (PMID 40931149, 2025). "PAX6 exhibits a multifaceted role in cancer progression, with its function intricately influenced by cellular context, epigenetic regulation, and non-coding RNA interactions." (PMID 40506992, 2025). "It is worth emphasizing that we have identified a novel function of PAX6 in the regulation of NE cancer cells, which extends its role besides a coordinator of neural development in the CNS or as a key regulator of the development and maintenance of the eyes." (PMID 38745318, 2024). "HHEX caused a repression of a series of neural stemness genes or/and genes promoting cancer, Sox1, Sox2, Myc, Cdh2, Vim, Hes1, Zic1, Pax6, Ezh2, and Lsd1." (PMID 34595169, 2021). "Consistently, PAX6 knockdown abolished the cancer-promoting effects of exosomal circ007293 in PTC cells in vitro." (PMID 34866540, 2021). "Other investigations have also supported PAX6 as an oncogene and have characterized its overexpression across numerous types of human cancers." (PMID 34866540, 2021). "Among these, we identify a number of known cancer genes (i.e., FOXL2, RUNX1T1), transcription factors (i.e., MEIS2), as well as LHX1 and PAX6 (which are also recurrently affected by mutations)." (PMID 33741928, 2021). "Meanwhile, NOL4, PAX6, TRIM58, and ZNF382 promoter methylation was also associated with the occurrence of many cancers." (PMID 31956659, 2019). "A detailed inspection of the common genes with most abundant dmCpGs in aging and cancer revealed a similar trend toward DNA hypermethylation at the boundaries of the gene PAX6." (PMID 29504244, 2018). "Only two groups have evaluated the prognostic impact of PAX6 in cancers using gene expression data obtained from clinical samples." (PMID 29568088, 2018). "Examples of TFs that control morphogenesis and play a role in cancer that were identified to oscillate in our data include PAX6 and GLI1." (PMID 29228002, 2017). "We indeed observed that expression level of PAX6 was also significantly in SCLC higher than that in NSCLC, indicating that upregulation of PAX6 might play a general role on promotion of NE trans-differentiation in cancers." (PMID 38745318, 2024). "Furthermore, two cells displayed high expression of stem cell markers, GATA2 and Pax6, suggesting that they were cancer stem‐like cells (red arrowheads)." (PMID 33932101, 2021). "In several types of cancer, low PAX6 expression results in a worse prognosis." (PMID 33182335, 2020). "Because many studies have shown that EMT confers resistance to chemotherapy and cancer stem cells exhibit chemoresistance, we suspected that PAX6 might affect the chemotherapeutic response by regulating stem cell transformation." (PMID 31024010, 2019). "Furthermore, higher SMAD3 and PAX6 protein expression was observed in the cancer cell lines compared with the healthy human lung epithelial cells (P < 0.01)." (PMID 30594196, 2018). "WA induces oxidative stress in cancer cells and that may be the reason for WT cells being more sensitive to the treatment compared to PAX6 KO cells." (PMID 29716531, 2018).
cancer (continued). "However, only a limited number of studies have investigated PAX6 expression in human malignancies, its biological role in cancer and possible effects on survival." (PMID 29568088, 2018). "The transcription factor PAX6 is expressed in various cancers." (PMID 29716531, 2018). "We observed that the promoter sequences of these translation elongation factor genes harbour binding sites for transcription factors which are commonly deregulated in the pathogenesis of human cancers, such as cFos, cJun, c-Ets1, Sp1, Sp3, Pax2 and, Pax6 among others." (PMID 29342219, 2018). "PAX6 is cancer-dependent and has different signaling pathways in different tumors." (PMID 24454925, 2014). "Although U251 cells and other cancer cells have ongoing chromosomal- and chromosome structure instabilities including variation in chromosome number, it is unclear whether chromosome 11, where PAX6 is located, is amplified." (PMID 29716531, 2018). "Hence, the Pax6-mediated repression of AR activity may be important and relevant in certain tissues, and also in specific cancer cells aberrantly expressing both proteins." (PMID 21935435, 2011). "In LUAD, MethSig cancer genes with an MR/MN greater than 1, including the HOX genes PAX6 and ITGA8, were enriched for cancer progression pathways, such as motility, tissue development and morphogenesis, and transcription regulation." (PMID 40931149, 2025). "The expression of PAX6 is positively correlated with the expression of GLI and SOX2, driving cancer cells to a stem-like state." (PMID 38745318, 2024). "Curcumin also enhances neural differentiation of pluripotent embryonic carcinoma cells and induced NeuroD, TUJ1, and PAX6 expression through the Notch signaling pathway." (PMID 34944744, 2021). "Similar SMAD3 and PAX6 mRNA and protein expression was observed in the four cell lines, including the normal BEAS-2B human lung epithelial cells and H125, HCC827 and A549 cancer cell lines." (PMID 30594196, 2018). "QRT-PCR was utilized to investigate SMAD3 and PAX6 expression levels in 20 normal and 20 NSCLC cancer tissues." (PMID 30594196, 2018). "Thus, activation of the PAX6/STAT5A axis leads to a global downregulation of H4K20me3, triggers cancer cells lineage changing and confers a NE transcriptional profile in PCa cells." (PMID 38745318, 2024). "We hypothesize that this compound will have similar effects in other cancer cell types which also aberrantly express PAX proteins at a high level, particularly PAX2, and potentially PAX5, PAX6 or PAX8." (PMID 34722257, 2021). "The cancer-to-adjacent nontumorous tissue ratio of PAX6 mRNA expression for each individual was calculated." (PMID 24454925, 2014). "Importantly, target genes involved in epithelium development (RGMA, SHANK3, PAX6, PFN1, WNT4) and cancer (CBL, CYCS, FGF7, IGF1R, PTEN, PIK3CD, WNT4) address to a further role in the onset of epithelial abnormalities and oncogenesis." (PMID 23936163, 2013). "Elucidating the specific mechanisms involved in the competition between Pax6 and SPBP for binding to AR, may result in important knowledge in the field of targeting AR coregulators for new cancer therapeutics." (PMID 21935435, 2011). "Binding that was induced in cancer, but not in the normal tissues, was displayed by the transcription factors E2F1, AP3, LIII-BP, PAX6, ADD-1, and CCAC." (PMID 25861239, 2015).
infection (22 papers, 2011 to 2025). The state of being infected such as from the introduction of a foreign agent such as serum, vaccine, antigenic substance or organism. "BEAS-2B cells were also infected with PAX6 knockdown or overexpression vectors, and the infection efficiency was measured by western blotting and RT-qPCR." (PMID 31024010, 2019). "Pax6 or Six3 expression vectors were introduced into mES or hES cells by transfection or lentiviral infection and the differentiating ES cells analyzed for lens marker expression." (PMID 25517354, 2014). "Flag+/Pax6+ cells, which were Olig2+ at the time of infection, migrated tangentially and were also localized to the SVZ (∼42%), RMS (∼41%) and olfactory bulb (∼2%)." (PMID 21698109, 2011). "It would be interesting to explore in the future whether PAX6 is required for shaping immune responses to infection by oomycetes or other natural pathogens in different animal contexts." (PMID 37725647, 2023). "AAV-2-TP-7 infection of WT islets resulted in overexpression of PAX6 in 43% of the infected cells." (PMID 30290306, 2018). "By 14 and 24 days post-infection, Pax6 lentivirus-infected H1 hES cells exhibited expression of γA-crystallin, Prox1, and Tdrd7, similar to expression of the homologous mouse proteins in G4 and Pax6-GFP mES cells." (PMID 25517354, 2014). "Conversely, expression levels of ectodermal (Pax6, Gfap, Neurod1, and Olig1) or mesendoderm (Flk1, Eomes, Hnf1b, and Mixl1) markers either not enhanced or only weakly increased after Cre infection." (PMID 40216251, 2025). "According to our protocol, infection was performed on the hiPSC level; subsequent puromycin selection was performed to enrich for S-, SO-, or SON-hiPSC and followed by neural induction to generate PAX6+ and OLIG2+ neural precursor cells (NPCs)." (PMID 35053357, 2022). "Transcripts for canonical β-cell markers including PDX1, FOXA2, G6PC2, and PAX6 were present at low levels and also decreased following infection but were not amongst the top 1000 differentially expressed transcripts." (PMID 32093375, 2020).